RNU6-180P (RNA, U6 small nuclear 180, pseudogene)
Gene: Small nuclear RNA gene on chromosome 1 (229,383,128 to 229,383,188, forward strand). Ensembl gene ENSG00000252506.
Homologues: Orthologues: chimpanzee U6 (92% identical), mouse Gm22381 (87% identical), pig U6 (80% identical), guinea pig U6 (77% identical), dog U6 (75% identical), guinea pig U6 (75% identical). Paralogues in human: RNU6-15P (95% identical), RNU6-1 (93% identical), RNU6-11P (93% identical), RNU6-1255P (93% identical), RNU6-12P (93% identical), RNU6-13P (93% identical), RNU6-154P (93% identical), RNU6-17P (93% identical), RNU6-18P (93% identical), RNU6-2 (93% identical), RNU6-21P (93% identical), RNU6-25P (93% identical), and 1286 more.